CCL4 (C-C motif chemokine ligand 4)
Diseases named in the same sentence as CCL4 in open-access papers (continued):
Sharing a sentence is not in itself a finding about the gene and the disease.
Ascites (3 papers, 2015 to 2023). Accumulation of fluid in the peritoneal cavity (between the layers of the peritoneum that lines the abdomen). "The rate of development of ascites in the CCL4 group was similar 7 days after IM (IM 3 (38%) vs. LAP 1 (14%), p = 0.5)." (PMID 34489738, 2021). "The combination of inflammatory markers and clinical variables favoured five inflammatory markers (TWEAK, CCL4, HGF, TRANCE and IL-33) and one clinical variable (ascites) with an AUROC of 0.73 and 95% CI [0.57;0.88]." (PMID 37973887, 2023). "No animals in in BDL and CCL4 groups developed ascites 2 days after IM, also none of the animals belonging to the PPVL groups developed ascites." (PMID 34489738, 2021).
B-cell lymphoma (3 papers, 2017 to 2024). "Moreover, evaluation of the CCL3 and CCL4 levels may be helpful for selecting B-cell lymphoma patients likely to benefit from doxorubicin treatment in combination with the velcade or ibrutinib." (PMID 33146700, 2020). "Large amounts of CCL3 and CCL4 accumulated in the culture medium of EBNA2-expressing cell lines (BJAB, U2932, DG75, and Toledo) and primary B cell lymphoma cells." (PMID 28036258, 2017). "Additionally, noteworthy genes, including IKZF2, CCL4, SAA1, and CD40, exhibited differential expression in the TCL group compared to the B-cell lymphoma (BCL) group." (PMID 39911484, 2024).
bipolar disorder (3 papers, 2021 to 2024). A disorder of the brain that causes unusual shifts in mood, energy, activity levels and the ability to carry out day-to-day tasks. "Another study focusing on biomarkers to differentiate unipolar and bipolar disorder, found that patients diagnosed with bipolar disorder, had high levels of CCL4 than unipolar counterparts." (PMID 34755124, 2021).
bladder cancer (3 papers, 2021 to 2024). "The results showed that in bladder cancer, FLT3LG not only exhibited significant positive correlations with immune checkpoints (CTLA416, IDO117), cytokines and chemokines (TNFSF13B, TNFRSF14, CXCR3, CCL4) but also exhibited the closest association with genes related to HLA18." (PMID 38213738, 2024). "By means of a 34‐cytokine and chemokine immunoassay panel, we revealed that chemokines including CCL3, CCL4, CCL5, CXCL9, and CXCL10, are robust negative correlated with expression of BCAT2 in human and murine bladder cancer cell." (PMID 36642843, 2023).
brain inflammation (3 papers, 2013 to 2024). "Another study pointed out that the OA2 microglial cell subset promotes age-related brain inflammation by expressing some unique inflammatory signals (such as Lgals3 Cst7 Ccl4 Ccl3 Il1b)." (PMID 39440247, 2024). "Several immune cell chemoattractants (Ccl4, Ccl7, Cxcl9) are featured in this network, suggesting recruitment of monocytes, NK cells and T-cells to the site of brain inflammation." (PMID 23853600, 2013). "Notably, we discovered a strong correlation between the serum and CSF levels of CCL4 in the brain inflammation group." (PMID 39364412, 2024). "In our correlation analysis in serum and CSF, we found that CCL4 was significantly correlated between serum and CSF in the brain inflammation group (r = 0.92, 95% CI = 0.20–0.99, p = 0.027), whereas no other factors showed significant differences between groups." (PMID 39364412, 2024). "Our findings revealed that the serum levels of IL-4, IFN-α, IFN-γ, IL-6, TNF-α, CCL4, P-cadherin, TRAIL, CCL11, and VEGF were significantly higher in cases of brain inflammation compared with brain gliomas." (PMID 39364412, 2024). "ROC analysis of immunological molecules in serum and CSF showed that the expression levels of IL-4, IFN-α, IFN-γ, IL-6, TNF-α, CCL4, CCL11, and VEGF exhibited high sensitivity and specificity in distinguishing between brain inflammation and brain tumor groups (p < 0.05)." (PMID 39364412, 2024).
cervical cancer (3 papers, 2015 to 2022). A primary or metastatic malignant neoplasm involving the cervix. "In addition, LDHA, CCL4, and PKM were reported to be associated with the development, proliferation, or progression of cervical cancer cells." (PMID 36284631, 2022).
dementia (3 papers, 2006 to 2022). Loss of intellectual abilities interfering with an individual's social and occupational functions. "The results show that CSF chemokine concentration of MCP-1/CCL2, MIP-1α/CCL3, MIP-1β/CCL4, RANTES/CCL5, IL-8/CXCL8 and fractalkine/CX3CL1 is positively correlated with the severity of dementia and the viral load, indicating HIV induced brain damage." (PMID 16712719, 2006). "CSF samples with undetectable CCL3, CCL4 or CCL5 levels were almost entirely from nondemented patients, and detectable CSF CCL3 and CCL4 were both associated with dementia." (PMID 35865985, 2022).
encephalitis (3 papers, 2016 to 2025). An acute inflammatory process affecting the brain parenchyma. "Alteration of CCL-4, CCL-17, CCL-20, CXCL10, CXCL-13, and TNF-α, IFN-γ, IL-2, IL-4, IL-5, IL-6, IL-9, IL-10, and IL-22 have been reported in the CSF or serum/plasma of patients with encephalitis." (PMID 40717731, 2025). "Concentrations of CCL3 and CCL4 in csf were not increased in any of the meningitis/encephalitis groups in comparison with controls and were not higher in csf than in serum, clearly not forming a chemotactic gradient towards cns." (PMID 26906062, 2016).
head and neck squamous cell carcinoma (3 papers, 2018 to 2024). A squamous cell carcinoma that arises from any of the following anatomic sites: lip and oral cavity, nasal cavity, paranasal sinuses, pharynx, larynx, and salivary glands. "An abnormal concentration of CCL4 is detectable in human head and neck squamous cell carcinoma (HNSCC), but the association between its level and the prognosis of HNSCC remains controversial." (PMID 39483474, 2024).
Hepatic Injury (3 papers, 2016 to 2022). "Administration of TQ at the dose of 100 mg/kg by oral gavage in the rats with CCL4 induced liver toxicity showed significant improvement form the deleterious effect of CCL4." (PMID 28983249, 2017).
Hypertension (3 papers, 2022 to 2024). The presence of chronic increased pressure in the systemic arterial system. "Meanwhile, we found that C5AR1, CCL4L2, CCL4, CCL20, CD163, CXCL3, and CXCL12 were only expressed in disease a, suggesting the recruitment of inflammatory factors and promotion of the inflammatory response were both more obvious in hypertension-induced AD." (PMID 35800890, 2022).
inflammatory bowel disease (3 papers, 2019 to 2025). A spectrum of small and large bowel inflammatory diseases of unknown etiology. "Our MR study provides genetic evidence supporting the role of several inflammatory cytokines (CD6, CCL4) in mediating the impact of lipidome on inflammatory bowel diseases." (PMID 40937162, 2025). "In the mediation analysis, we identified two circulating inflammatory proteins (CD6, CCL4) playing a mediating role between lipidome and inflammatory bowel disease." (PMID 40937162, 2025).
ischemic brain disease (3 papers, 2018 to 2024). "In addition, many enriched inflammatory markers after cerebral ischemia, including interleukins IL-11 and IL-6, chemokines (Ccl4, Ccl2, Ccl5) and serum amyloid A (Saa3), were observed to be up-regulated consistent with reports elsewhere." (PMID 29896414, 2018).
mesothelioma (3 papers, 2019 to 2024). A usually malignant and aggressive neoplasm of the mesothelium which is often associated with exposure to asbestos. "Mesothelioma cells attract monocytes in the TME though releasing some chemokines, such as chemokine (C-C motif) ligand 2 (CCL2), chemokine (C-C motif) ligand 4 (CCL4), chemokine (C-C motif) ligand 5, and C-X-C motif chemokine ligand 12 (CXCL12)." (PMID 38259475, 2023). "Chemokine signals that attract monocytes in mesothelioma include CCL2, CCL4, CCL5, and CXCL12 and these appear to be of mesothelioma cell origin." (PMID 31867277, 2019). "Interestingly, chemokines involved in monocyte/macrophage recruitment and mobilization such as CCL2, CCL3, CCL4, and CCL7 were downregulated in the mesothelioma cell line compared to two other tested cell lines." (PMID 39768223, 2024).
muscular dystrophy (3 papers, 2016 to 2024). Muscular dystrophy (MD) refers to a group of more than 30 genetic diseases characterized by progressive weakness and degeneration of the skeletal muscles that control movement. "Our data showing elevated levels of several CC-motif-containing chemokines extend prior studies showing increased expression CCL2, CCL3, and CCL4 in muscle biopsies obtained from animal models and human patients suffering from muscular dystrophy or inflammatory myopathies." (PMID 33138863, 2020).
myocardial infarction (3 papers, 2016 to 2024). Gross necrosis of the myocardium, as a result of interruption of the blood supply to the area, as in coronary thrombosis. "Then, immunohistochemistry was used to study the expression of CCL4 in a mouse myocardial infarction model." (PMID 39809140, 2024). "H9c2 cardiomyocytes simulated myocardial infarction under hypoxia, and the results showed that the expression of gene CCL4 was increased." (PMID 39809140, 2024).
myositis (3 papers, 2020 to 2024). "Moreover, higher circulating levels of myositis biomarkers, including interleukin 23 (IL-23) and macrophage inflammatory protein [CC motif chemokine ligand 4 (CCL4)], were detected in MBKO mice." (PMID 39531828, 2024).
pancreatic cancer (3 papers, 2023 to 2024). "While the direct anti-cancer effects of CCL4 have been demonstrated in pancreatic cancer cells, its potential impact on BC remains unexplored." (PMID 39518934, 2024). "In our previous study, we observed that a combination of CXCL1, IL10, and CCL4 significantly impacted pancreatic cancer cells." (PMID 39518934, 2024). "CCL4, CCL5, CXCL9, and CXCL10 are associated with CD8+ T cells in pancreatic cancer." (PMID 38887558, 2024). "We were able to show that the serum of exercise-trained patients with advanced-stage pancreatic cancer (PC) leads to the release of certain myokines, such as C-X-C motif ligand 1 (CXCL1), Interleukin 10 (IL10), and C-C motif chemokine ligand 4 (CCL4), from contracting skeletal muscle." (PMID 39518934, 2024).
pneumonitis (3 papers, 2012 to 2020). An inflammatory process affecting the lung parenchyma. "It is also known that increased concentration of cytokines, such as IL-8, CCL4, and G-CSF, might influence macrophages, neutrophils, and lymphocytes chemotaxis and promote pneumonitis and subsequent fibrosis formation." (PMID 33598430, 2020). "SsRNA stimulation of human leukocytes induced cytokines/chemokines similar to those observed in murine SARS-CoV pneumonitis including IL-1α, IL-1β, IL-6, TNF, CXCL8 (IL-8), CCL2 (MCP-1), CCL3 (MIP-1α), and CCL4 (MIP-1β)." (PMID 23236475, 2012).
rectal cancer (3 papers, 2019 to 2021). A primary or metastatic malignant neoplasm that affects the rectum. "When investigating the expression of these chemokines by rectal cancer-infiltrating pDCs, we observed that CCL4- or CXCL10-expressing pDCs are present in the majority of post-nRCT tumor specimens, whereas they are absent in pre-nRCT tissue samples." (PMID 30984181, 2019).
renal fibrosis (3 papers, 2019 to 2025). A final common manifestation of a wide variety of chronic kidney diseases characterized by glomerulosclerosis and tubulointerstitial fibrosis. "Overall, these findings revealed a concerted shift in B cell states during renal fibrosis, marked by the expansion of a pro-inflammatory NaiveB_Ccl4 subset—potentially recruiting innate immune cells via chemotaxis—and the terminal differentiation of antibody-secreting plasma cells." (PMID 41269996, 2025).
tauopathy (3 papers, 2024 to 2025). Neurodegenerative disorders involving deposition of abnormal tau protein isoforms (tau proteins) in neurons and glial cells in the brain. "CCL-4 is linked to microglial transcription related to Aβ plaque phagocytosis and emerged as a top transcript in rodent models of aging, amyloidosis, and tauopathy." (PMID 39922907, 2025). "recently showed that the cytokine receptor CCR5 (which binds IFN‐I‐associated ligands for MIP‐1a/CCL3, MIP‐1b /CCL4, and CCL5) promoted tauopathy in in vivo models, partially through the regulation of autophagy." (PMID 37849026, 2024).
Thrombocytopenia (3 papers, 2022 to 2025). A reduction in the number of circulating thrombocytes. "Clinical studies in endemic areas have described a correlation between DENV disease outcome and the levels of CCL4 which are intimately related to hypotension, thrombocytopenia, and hemorrhagic shock." (PMID 35711447, 2022). "On the other hand, in our model, a significant increase in platelets was observed, which does not occur with other fibrosis inducers like CCL4, which instead develop thrombocytopenia." (PMID 36411771, 2022).
acute kidney injury (2 papers, 2014 to 2021). Sudden and sustained deterioration of the kidney function characterized by decreased glomerular filtration rate, increased serum creatinine or oliguria. "Transgene-enforced overexpression of SAT1 accelerates aging in mice as it enhances carcinogenesis, while its knockout protects against liver and kidney ischemia-reperfusion damage, CCL4-induced acute liver injury, and endotoxin- or cisplatin-induced acute kidney injury." (PMID 34517343, 2021).
alveolitis (2 papers, 2022 to 2024). "In addition, we also found that FHP-specific macrophage subsets highly expressed CCL4, implicating the importance of chemotactic function in the development of fibrotic hypersensitivity pneumonitis." (PMID 35091537, 2022). "Reflecting the significant reduction in expression of chemokines (CCL3, CCL4, CXCL1, CXCL2, and CXCL10) in the lung, the levels of alveolitis in PKD1mKO at 24 h after the S. rectivirgula exposure was also significantly reduced compared to the levels of alveolitis in WT." (PMID 39464896, 2024).
aneurysm (2 papers, 2009 to 2015). Bulging or ballooning in an area of an artery secondary to arterial wall weakening. "In addition, we measured expression of potent mononuclear chemoattractants and found that chemokine CCL2 had significantly lower expression in aneurysms than in controls, while the chemokine CCL4 showed only a tendency to a lower expression in aneurysms." (PMID 26539497, 2015).
Autoimmunity (2 papers, 2018 to 2022). The occurrence of an immune reaction against the organism's own cells or tissues. "MC-secreted cytokines and chemokines encoded by IL1B, TNF, CCL3, and CCL4, all of which contribute to autoimmunity and inflammation, may stimulate other cell populations expressing their homologous receptors." (PMID 36301664, 2022). "A role for CCL3, CCL4, CCL5 and their receptor CCR5 in Treg mediated suppression has been previously reported in autoimmunity and cancer and we demonstrate through blockade experiments both these pathways to be of fundamental importance in cells from IGRA-ve controls." (PMID 30231065, 2018).
bacteremia (2 papers, 2018 to 2025). "In our study, we found six of the soluble mediators analyzed that differentiated between patients with and without bacteremia: TNF-α, CCL4, TIMP-1, VCAM-1, ICAM-1, and E-selectin." (PMID 29681903, 2018). "Using unsupervised hierarchical clustering, we found that TNFα, CCL4, E-selectin, VCAM-1, ICAM-1, and TIMP-1 could be used to discriminate between patients with and those without bacteremia." (PMID 29681903, 2018).
bone metastasis (2 papers, 2025 to 2026). Transfer of a neoplasm from its primary site to bones. "Bone metastasis linked with CCL4 (OR = 0.991, p = 0.017) and CCL2 (OR = 0.996, p = 0.001)." (PMID 41957068, 2026). "Six proteins (CSF-1, CCL4, CCL3, CD83, IL-12, and CD244) and three clinical characteristics (LDH levels, bone metastasis status, and liver metastasis status) were incorporated into the predictive model." (PMID 40404633, 2025).
Burkitt lymphoma (2 papers, 2021 to 2025). A rare form of malignant mature B-cell non-Hodgkin lymphoma. "We confirm that CCR1 and CCL4 expression in Burkitt’s lymphoma cells requires full latent gene expression." (PMID 40389409, 2025). "Previous work showed that LMP1 can induce CCL4 release and that CCR1 surface expression in EBV-positive Burkitt’s lymphomas requires full latent gene expression." (PMID 40389409, 2025). "To establish whether these viral genes control CCL4 and CCR1 expression in infected B cells, we first monitored their expression in an early and a late passage of the MUTU Burkitt’s lymphoma cell line." (PMID 40389409, 2025). "In addition, in vitro and in vivo studies in Burkitt lymphoma cells suggest that CCL3 and CCL4 contribute to the rituximab-induced activation of the innate immunity system." (PMID 36046113, 2021).
chlamydia (2 papers, 2008 to 2022). "CCL3 and CCL4 are also CCR5 ligands, but these chemokines were not remarkably elevated compared to CCL5, which was the most abundant CCR5 ligand expressed during the early stages (i.e., < 7 days) of chlamydial infection." (PMID 18700040, 2008).
chronic endometritis (2 papers, 2020 to 2024). A non-granulomatous or granulomatous chronic inflammation of the endometrium. "Also, the mechanism of control over the rate of gene transcription or transcriptional regulation is altered in genes involved in chronic endometritis and the inflammatory response (IL-11, CCL4), growth factors (IGFBP1), and apoptotic proteins (BCL2, BAX, CASP8) in infertile patients." (PMID 33329514, 2020). "For instance, chronic endometritis is characterized by a modified gene expression profile involving proinflammatory mediators like IL11, IL17, TGF-β, CCL4, IGFBP1, and CASP8, contrasting with the gene expression profile observed in normal fertile women during the implantation window." (PMID 38927030, 2024).
chronic hepatitis C (2 papers, 2017 to 2018). "Therefore, it has emphasized the importance of CCL4 among other serum chemokines, especially in considering the future shorter duration of treatment for chronic hepatitis C patients receiving shorter duration of interferon-free DAAs." (PMID 29284412, 2017). "Furthermore, CCL3, CCL4, CCL5, CXCL9, CXCL10 and CXCL11 were found to increase in both liver and peripheral blood during chronic hepatitis C in several studies." (PMID 29284412, 2017).
colorectal tumor (2 papers, 2022). "As the targeted migration of CRC patient-derived Treg cells towards CCL4 could be demonstrated in vitro, it thus appears likely that CCL4 can also support the Treg cell-mediated immune evasion of colorectal tumors." (PMID 36428508, 2022).
dengue haemorrhagic fever (2 papers, 2018 to 2024). "The CCL4 and five chemokines appear to have a positive prognostic significance, as their levels are reduced in patients with dengue haemorrhagic fever." (PMID 39768136, 2024).
diffuse large B-cell lymphoma (2 papers, 2017 to 2020). "Recent findings support CCL3 and CCL4 protein concentrations as biomarkers for B cell receptor (BCR) pathway activation and prognosis in diffuse large B cell lymphoma (DLBCL)." (PMID 28146424, 2017). "Interestingly, Ccl4 was already identified as a candidate for biomarker for BCR pathway activation and prognostic in diffuse large B cell lymphoma and as an inflammation-related diseases biomarker (Olink proteomics)." (PMID 32659965, 2020).
dysplasia (2 papers, 2024 to 2025). A usually neoplastic transformation of the cell, associated with altered architectural tissue patterns. "In normal mucosa, in turn, dysplasia grade affected the CCL4 amount as the protein was more abundant in the tissue surrounding polyps with high-grade dysplasia." (PMID 38338661, 2024).
fungal infection (2 papers, 2013 to 2018). "In addition, genetic studies revealed single nucleotide polymorphisms (SNPs) in CCL3 and CCL4, which are significantly correlated to fungal infections." (PMID 30563459, 2018). "Among these genes those related to host defense against fungal infection were upregulated between 2 and 6 hours of exposure to the fungus, such as IL-1β, IL-8, CXCL2, CCL4, CCL3, and CCL20, coinciding with an increase in phagocytosis." (PMID 23984400, 2013).